CNEP1R1 (CTD nuclear envelope phosphatase 1 regulatory subunit 1)
Description:
Forms with the serine/threonine protein phosphatase CTDNEP1 an active complex which dephosphorylates and may activate LPIN1 and LPIN2. LPIN1 and LPIN2 are phosphatidate phosphatases that catalyze the conversion of phosphatidic acid to diacylglycerol and control the metabolism of fatty acids at different levels. May indirectly modulate the lipid composition of nuclear and/or endoplasmic reticulum membranes and be required for proper nuclear membrane morphology and/or dynamics. May also indirectly regulate the production of lipid droplets and triacylglycerol.
Synonyms: NEP1-R1; C16orf69; TMEM188; FLJ38101; NEP1R1; TMP125
Tractability: Antibody: UniProt predicts a signal peptide or a membrane-spanning region. PROTAC: its protein half-life has been measured.
Gene: Protein-coding gene on chromosome 16 (50,024,410 to 50,037,088, forward strand). Ensembl gene ENSG00000205423.
Subcellular location: Nucleus membrane; Cytoplasm
Subcellular location (Human Protein Atlas): Cytosol
Pathways (Reactome):
Cell Cycle: Depolymerization of the Nuclear Lamina
Gene Ontology:
Molecular function: protein binding; protein phosphatase regulator activity
Biological process: positive regulation of triglyceride biosynthetic process; protein localization to nucleus
Cellular component: cytoplasm; cytosol; Nem1-Spo7 phosphatase complex; nuclear membrane; nuclear envelope
Genetic constraint (gnomAD): Loss-of-function variants: 1 observed, 0.32 expected, observed/expected ratio (o/e) 3.1. That is too few expected variants to judge how well the gene tolerates losing a copy. Missense variants: 9 observed, 5.24 expected, observed/expected ratio (o/e) 1.72, 90% interval 0.94 to 1.95. Synonymous variants: 5 observed, 1.76 expected, observed/expected ratio (o/e) 2.84.
Homologues: Orthologues: chimpanzee CNEP1R1 (100% identical), dog CNEP1R1 (100% identical), guinea pig CNEP1R1 (100% identical), macaque CNEP1R1 (100% identical), mouse Cnep1r1 (100% identical), rat Cnep1r1 (99% identical), tropical clawed frog cnep1r1 (98% identical), pig CNEP1R1 (96% identical), rabbit CNEP1R1 (94% identical), zebrafish cnep1r1 (94% identical), Drosophila melanogaster Cnep1r2 (58% identical), Caenorhabditis elegans nepr-1 (42% identical), and 1 more.
Diseases named in the same sentence as CNEP1R1 in open-access papers:
CNEP1R1 is named in the same sentence as 2 diseases in open-access papers, as found by Europe PMC text mining. Sharing a sentence is not in itself a finding about the gene and the disease. The quoted sentences say what the papers report.
infection (1 paper, 2020). The state of being infected such as from the introduction of a foreign agent such as serum, vaccine, antigenic substance or organism. "Only 3 (ABCF3, CNEP1R1, TWF1) out of 11 genes shared between moDC and cDC2 were up-regulated in response to infection." (PMID 33365028, 2020).
CNEP1R1 also shares sentences with these, for which no sentence is quoted: cancer (1 paper).